MIR5196 (microRNA 5196)
Synonyms: hsa-mir-5196; mir-5196
Gene: MicroRNA gene on chromosome 19 (35,345,513 to 35,345,627, forward strand). Ensembl gene ENSG00000284034.
Homologues: Orthologues: chimpanzee MIR5196 (100% identical).